HELZ2 (helicase with zinc finger 2)
Description:
Multifunctional nuclear protein involved in RNA surveillance, nuclear receptor-mediated transcriptional regulation, and the restriction of mobile genetic elements as part of the innate immune response. Degrades highly structured RNAs through its concerted ATP-dependent RNA helicase and 3' to 5' exoribonuclease activities. Shows a strong preference for pyrimidine over purine residues for its nuclease activity. Acts as a transcriptional coactivator for a number of nuclear receptors including PPARA, PPARG, THRA, THRB and RXRA. In addition, regulates lipid metabolism independently of PPARs by controlling the stability of Apob mRNA, which encodes a protein essential for lipoprotein assembly and secretion. Also contributes to adipocyte differentiation through interactions with the splicing factor proline- and glutamine-rich protein SFPQ and THRAP3.
Synonyms: PDIP1; KIAA1769; PRIC285; PDIP-1
Tractability: PROTAC: ubiquitination databases record sites on it; its protein half-life has been measured.
Gene: Protein-coding gene on chromosome 20 (63,558,086 to 63,574,239, reverse strand). Ensembl gene ENSG00000130589.
Subcellular location: Cytoplasm
Pathways (Reactome):
Circadian clock: BMAL1:CLOCK,NPAS2 activates circadian expression; Expression of BMAL (ARNTL), CLOCK, and NPAS2; RORA,B,C and NR1D1 (REV-ERBA) regulate gene expression
Metabolism: Activation of gene expression by SREBF (SREBP); PPARA activates gene expression; Regulation of lipid metabolism by PPARalpha
Cellular responses to stimuli: Cytoprotection by HMOX1; Heme signaling
Developmental Biology: Transcriptional regulation of white adipocyte differentiation
Organelle biogenesis and maintenance: Transcriptional activation of mitochondrial biogenesis
Gene Ontology:
Molecular function: ATP hydrolysis activity; exoribonuclease II activity; protein binding; RNA binding; RNA helicase activity; transcription coactivator activity; 3'-5' RNA helicase activity; 3'-5'-RNA exonuclease activity; helicase activity; metal ion binding; RNA nuclease activity
Biological process: positive regulation of transcription by RNA polymerase II; regulation of lipid metabolic process
Cellular component: cytoplasm; membrane; cytosol; nucleoplasm; P granule
Genetic constraint (gnomAD): Loss-of-function variants: 145 observed, 167.55 expected, observed/expected ratio (o/e) 0.87, 90% interval 0.75 to 0.99. The upper end of that interval is the gene's LOEUF score, 0.99, which puts it in group 4 of 6, group 1 being the genes least tolerant of losing a copy. Missense variants: 3,690 observed, 3,456.4 expected, observed/expected ratio (o/e) 1.07, 90% interval 1.04 to 1.1. Synonymous variants: 1,705 observed, 1,499.9 expected, observed/expected ratio (o/e) 1.14, 90% interval 1.09 to 1.18.
Homologues: Orthologues: chimpanzee HELZ2 (98% identical), macaque HELZ2 (94% identical), guinea pig HELZ2 (72% identical), rat Helz2 (70% identical), mouse Helz2 (70% identical), pig HELZ2 (64% identical), tropical clawed frog helz2 (42% identical), zebrafish helz2a (38% identical), zebrafish helz2b (30% identical), zebrafish si:ch211-183d5.1 (20% identical), Drosophila melanogaster Setx (13% identical), Caenorhabditis elegans znfx-1 (12% identical). Paralogues in human: SETX (12% identical), UPF1 (10% identical), MOV10L1 (8% identical), DNA2 (8% identical), HELZ (8% identical), ZNFX1 (8% identical), AQR (7% identical), MOV10 (7% identical), IGHMBP2 (7% identical), CT55 (2% identical).
Diseases named in the same sentence as HELZ2 in open-access papers:
HELZ2 is named in the same sentence as 25 diseases in open-access papers, as found by Europe PMC text mining. Sharing a sentence is not in itself a finding about the gene and the disease. The quoted sentences say what the papers report.
Flavivirus Infections (2 papers, 2024). Infections with viruses of the genus FLAVIVIRUS, family FLAVIVIRIDAE. "Interestingly, HELZ2, apreviously described host factor that restricts direct flavivirus infection, wasalso enriched." (PMID 39377586, 2024).
Hypertension (2 papers, 2020 to 2025). The presence of chronic increased pressure in the systemic arterial system. "A high-throughput assay of small-molecule drugs revealed that guanabenz acetate (Ga), originally used to treat hypertension, possesses a high affinity constant against HELZ2, and its administration activates LEPRB expression in HepG2 cells in vitro." (PMID 32792584, 2020). "The other drugs used as anti-hypertension treatment via activation of the α2-adrenergic receptor include clonidine hydrochloride, methyldopa and guanfacine hydrochloride, but these drugs showed the very low affinity constants (over 10–6 M) for HELZ2." (PMID 32792584, 2020).
autoimmune disease (1 paper, 2016). A disorder resulting from loss of function or tissue destruction of an organ or multiple organs, arising from humoral or cellular immune responses of the individual to their own tissue constituents. "This was the first evidence to show that the lipid metabolism-related gene, HELZ2 was linked with autoimmune disease, at least for primary biliary cirrhosis in Chinese Han population." (PMID 27047549, 2016). "In this study, a nonsynonymous SNP in the coding region of HELZ2 was identified to significantly associated with PBC.This was the first genetic analysis to associate HELZ2 with the pathogenesis of autoimmune disease, at least for primary biliary cirrhosis in Han Chinese." (PMID 27047549, 2016). "The result was the first time to show evidence of the lipid metabolic gene HELZ2 related to autoimmune disease, at least in PBC of Chinese Han." (PMID 27047549, 2016). "Therefore, we speculated that HELZ2 might be associated with autoimmune diseases." (PMID 27047549, 2016). "Therefore, we inferred that HELZ2 might be associated with autoimmune diseases." (PMID 27047549, 2016).
colorectal adenocarcinoma (1 paper, 2018). The most common type of colorectal carcinoma. "For example, the P1772S variant in the HELZ2 gene is present in cutaneous melanoma and colorectal adenocarcinoma, the C1183S variant in PCDH12 is present in renal cell carcinoma and colorectal adenocarcinoma." (PMID 30301885, 2018).
dengue (1 paper, 2017). "Primary bone marrow derived macrophages from HELZ2 knockout mice, compared to wild type controls, exhibit enhanced dengue infectivity." (PMID 28265266, 2017). "We thus sought to determine whether HELZ2 interacts with a nuclear receptor known to regulate immune response and lipid metabolism, AHR, and identified HELZ2:AHR interactions via co-immunoprecipitation, found that AHR is a dengue IEG, and that an AHR ligand, FICZ, exhibits anti-dengue activity." (PMID 28265266, 2017).
depression (1 paper, 2021). "Additionally, four genes HELZ2, PTPRN2, GATA2, and ZNF624 were differentially expressed between depression cases and health controls." (PMID 34341332, 2021).
Hyperglycemia (1 paper, 2020). An increased concentration of glucose in the blood. "In the present study, we made an attempt to identify a Helz2-associated small-molecule drug that ameliorates fatty liver and hyperglycemia in HFD-induced obese mice." (PMID 32792584, 2020). "Reduction in Helz2 expression in obese mice attenuated hepatosteatosis and hyperglycemia, which prevented BW gain without detectable anorexia." (PMID 32792584, 2020).
primary biliary cirrhosis (1 paper, 2016). "However, precise molecular mechanism of the variant of HELZ2 with primary biliary cirrhosis should be elucidated further." (PMID 27047549, 2016). "Since it could affect liver regeneration, HELZ2 had the highly potentiality to contribute to the pathogenesis of primary biliary cirrhosis." (PMID 27047549, 2016).
Zika virus infection (1 paper, 2024). "HELZ2 is an interferon-stimulated helicase and nuclear factorcoactivator with previouslydescribed antiviral activity in the context of direct DENV and to alesser extent, Zika virus infection." (PMID 39377586, 2024).
infection (9 papers, 2016 to 2026). The state of being infected such as from the introduction of a foreign agent such as serum, vaccine, antigenic substance or organism. "HELZ2 appears to exert its anti-DENV activity by modulating host lipid metabolism following direct infection." (PMID 38712102, 2024). "In this assay, we found increased infection levels in cells with HELZ2 knockdown vs. vector controls (APM)." (PMID 28265266, 2017). "We tested HELZ2 knockdown effect on DENV RNA levels at a later time point (24 h post infection) using qRT PCR." (PMID 28265266, 2017). "Knockdown of HELZ2 in KO-IFNAR1 could further increase the DTMUV RNA level at later stages of infection." (PMID 36298780, 2022). "Thus, HELZ2 may be among a growingset of interferon-stimulated genes with both antiviral and proviral functions.HELZ2 appears to exert its anti-DENV activity by modulating host lipid metabolismfollowing direct infection." (PMID 39377586, 2024). "In response to ΔHA-Cre infection, all cell types were able to upregulate the putative protective ISG Helz2." (PMID 32790753, 2020). "In order to determine the lifecycle stage at which HELZ2 knockdown enhances DENV infection, we then performed a series of lifecycle assays in human hepatocytes, comparing infection in HELZ2 knockdown vs. vector control (APM) cells (Datasheet S3)." (PMID 28265266, 2017). "Lifecycles assays measuring effect of HELZ2 knockdown on DENV via early-infection RNA ISH, qRT PCR, western blot, immunofluorescence, and supernatant plaque assay reveal that HELZ2 appears to exert anti-DENV activity from early infection onward." (PMID 28265266, 2017).
tumor (5 papers, 2013 to 2025). "HELZ2 is a protein implicated in the peroxisome activity and the proliferation of tumor cells via PPAR-δ pathway activation." (PMID 30459932, 2018). "The three mutations found in cancer patients (D1601N, S1920L, and R1923L) eliminate the RNase activity of HELZ2, suggesting that they may promote tumor development by weakening the immune system." (PMID 41327353, 2025).
cancer (4 papers, 2018 to 2025). A tumor composed of atypical neoplastic, often pleomorphic cells that invade other tissues. "The results of interactive network analysis provide new perspectives on the role of hub genes, along with RYR2, ERBB2, PIK3CA, and HELZ2, with respect to the development of GC by querying multidimensional cancer genomics data in cBioPortal." (PMID 32801999, 2020). "HELZ2, ADM2 are also related with prognosis of various types of cancer." (PMID 37955724, 2023). "In contrast, some of the genes, including ENTHD1, HELZ2, PCDH12, CPNE4, and SHANK1, that are mutated in metastatic ACCs alone are completely novel and have not been functionally characterized in any cancer type until now." (PMID 30301885, 2018).
lung (1 paper, 2018). "Nevertheless, we observed that genes such as DNAH6, MUC5B, HELZ2, and KIAA0100 were frequently mutated in three of six lung ACC metastases." (PMID 30301885, 2018).
HELZ2 also shares sentences with these, for which no sentence is quoted: Hepatic steatosis (3 papers); Insulin resistance (2); breast carcinoma (1); cutaneous melanoma (1); cystadenoma (1); diabetes (1); endometrial cancer (1); gastric tumors (1); hyperlipidemia (1); Obesity (1); renal cell carcinoma (1); retinoblastoma (1).